LEPR (leptin receptor)
Diseases named in the same sentence as LEPR in open-access papers (continued):
Sharing a sentence is not in itself a finding about the gene and the disease.
Insulin resistance (continued). "Recent studies have associated LEPR gene variants with inflammatory traits like plasma fibrinogen and C-reactive protein levels, bone density and insulin resistance in nondiabetic obese patients." (PMID 19562039, 2009). "However, leptin receptor deficiency is just one of mechanisms of T2DM, and such a mechanism is rare, while hyperinsulinemia and insulin resistance, caused by other risk factors, including environmental factors, genetics and epigenetics, are more common in human T2DM." (PMID 35941186, 2022). "Notably, we have shown previously in mice with inducible insulin receptor ablation that the genetically caused insulin resistance drastically increased hepatic LEPR expression that at least in part absorbed the lack of hepatic insulin action in these mice." (PMID 30224299, 2018). "Moreover, serum BSP concentrations did not correlate with the patients’ body mass index (BMI) or markers for a deregulated metabolic state (serum levels of Adiponectin, Leptin, leptin receptor) or insulin resistance (serum levels of Insulin, C-peptide, HbA1c, HOMA)." (PMID 29950701, 2018). "LepR, soluble leptin receptor; Adipo, adiponectin; HOMA, homeostatic model assessment of insulin resistance; Gluc, fasting glucose; CRP, high-sensitivity C-reactive protein; TMAO, trimethylamine N-oxide." (PMID 41202005, 2025). "Homeostatic Model Assessment for Insulin Resistance (HOMA IR) was greater in subjects with homozygous dominant, 'GG' of LEPR (p=0.0409) and hyperinsulinemia (p=0.023) as compared to other genotypes." (PMID 36128550, 2022). "Inhibition of GCN2 by intraperitoneal injection of 3 mg/kg GCN2iB (a specific inhibitor of GCN2) every other day for 6 weeks also ameliorated hyperglycemia, insulin resistance, hepatic steatosis, and oxidative stress in HFD/STZ- and leptin receptor deletion (db/db)-induced T2D mice." (PMID 36009303, 2022). "The long-term hepatic outcome of untreated human leptin deficiency or leptin receptor mutation is not known; however, leptin receptor polymorphisms have been associated with NASH and insulin resistance in patients with NAFLD." (PMID 27899914, 2016). "However, deletion of PTP1B could not improve insulin resistance in leptin receptor mutant db/db mice." (PMID 36046814, 2022). "Given that leptin levels are increased in MASLD patients, and leptin promotes insulin resistance, we consider the negative relationship between FGF21 and LEPR as highly suggestive for FGF21 to improve insulin sensitivity by dampening leptin signalling." (PMID 39962359, 2025).
Hyperglycemia (117 papers, 2010 to 2026). An increased concentration of glucose in the blood. "The Enrichr-KG15 uses the Jensen lab database to augment the subnetwork, highlighting the associations of the LEPR gene with hyperinsulinism, fatty liver disease, infertility, cardiovascular system disease, and hyperglycemia." (PMID 41221514, 2025). "These mice carry a mutation in the leptin receptor and, at 15–16 weeks of age, are hyperphagic, obese and exhibit fasting hyperglycaemia." (PMID 38704026, 2024). "Genetically, diabetic leptin receptor-deficient db/db mice are obese and insulin resistant and display hyperglycemia at an early age and transition from β-cell compensation to failure with a pathophysiological sequence of events similar to human T2D." (PMID 34890851, 2022). "The db/db mouse model is characterized by leptin receptor deficiency, and displays hyperinsulinemia, hyperglycemia, and glucosuria phenotypes." (PMID 32194395, 2020). "In line with previous reports, ZSF1 rats with a homozygous leptin receptor mutation in our current study presented with metabolic derangements, including elevated body weight, hypercholesteremia, hyperglycaemia and hypertriglyceridemia." (PMID 31368189, 2019). "Diabetic db/db mice had a greater body weight, blood glucose level, and plasma osmolarity compared with WT mice, confirming the leptin receptor mutation is associated with chronic hyperglycaemia." (PMID 29339138, 2018). "In the in vivo study, leptin receptor-deficient mice treated with the GLP-1 gene developed mild hyperglycemia for eight weeks." (PMID 30065848, 2018). "Genetically, ZDF rats are leptin receptor deficient in and resistant to leptin, and therefor develop T2D with hyperglycemia and hyperinsulinemia." (PMID 25365428, 2014). "Many diabetic mouse models, such as leptin receptor-deficient db/db mice and mice where hyperglycemia is induced by streptozocin or galactose feeding, develop vascular and neural changes typical of early stages of DR." (PMID 23922490, 2013). "When leptin receptor mutation is introgressed into the Nidd2/of congenic strain, the rat showed hyperglycemia equivalent to that of the parental OLETF rat." (PMID 23304119, 2012). "In conclusion, the new congenic strain carrying single QTL derived from the OLETF rat shows severe hyperglycemia when combined with obese phenotype via leptin receptor mutation." (PMID 23304119, 2012). "Neuronal LEPR deletion induces diabetic phenotypes such as body weight increase, adiposity, and hyperglycemia in proportion to hypothalamic LEPR deficiency." (PMID 20624279, 2010). "Moreover, the MHW intake improved hyperglycemia, hyperinsulinemia, and the plasma triglyceride level with decreasing BW in diabetic db/db mice with genetically engineered leptin receptor deficiency at 3 months." (PMID 33922704, 2021). "Moreover, delayed bone remodelling caused by chronic hyperglycaemia in LepR−/− rats might have exacerbated the prevalence of those islands compared to bone of LepR+/+ rats." (PMID 37730735, 2023). "Another study demonstrated that XYS alleviated CUMS-induced depressive symptoms and hyperglycemia by modulating the Leptin Receptor (LepR)-Signal Transducer and Activator of Transcription 3 (STAT3)/PI3K cascade." (PMID 41535967, 2026). "Leptin receptor deficiency is a common feature of the ZDF rat model, which manifests with functional characteristics of T2DM such as hyperphagia, severe hyperglycemia, hyperlipidemia, hyperinsulinemia in males at 9–10 weeks of age." (PMID 41212880, 2025). "The leptin receptor (Lepr) has also been deleted in rats, and these animals show hyperphagia, obesity, hyperglycemia, and dyslipidemia." (PMID 33959146, 2021). "Previous studies have shown that leptin receptor (LepR) expression in GABAergic neurons mediates leptin action in reducing hyperglycemia in T1D6,14." (PMID 33976218, 2021). "Sh2b1ΔLepR males and females developed hyperglycemia and hyperinsulinemia compared to sex/age-matched LepR-Cre mice at 19–20 weeks of age." (PMID 32251290, 2020).
Hyperglycemia (continued). "In the past, several QTL have been identified in the mid-region of mouse chromosome 4 in the proximity of the leptin receptor gene (Lepr) relating to hyperglycemia and hypoinsulinemia." (PMID 33133152, 2020). "In the third model, the leptin receptor (LEPR) deficient db/db mice, hyperglycaemia combined with hyperlipidemia were observed in 12-week-old db/db mice, compared to wild type mice." (PMID 33186123, 2020). "We used ZDF rats characterized by a progressive β-cell dysfunction and a leptin receptor defect, which result in hyperglycemia." (PMID 24624334, 2014). "Future studies will be aimed at determining the exact contributions of both leptin-receptor signaling and additional metabolic, endocrine, and proinflammatory pathways induced by hyperglycemia in normal and malignant breast epithelial cells." (PMID 24260287, 2013). "Caloric restriction normalized weight in both leptin and LepR deficient mice; however, hyperglycemia was only improved in Lepob but not in LepRdb mice." (PMID 35159237, 2022). "Here, we report that the α7 nicotinic acetylcholine receptor (α7nAChR) agonist GTS-21 exerts a novel anti-inflammatory action to ameliorate DN, as studied using an inbred strain of Leprdb/db mice in which hyperglycemia and obesity co-exist owing to defective leptin receptor (Lepr) signaling." (PMID 36572735, 2022). "C57BL/6 background leptin receptor deficient (B6-db/db) homozygous mice reveal compensatory hyperplasia of β-cells and continued hyperglycemia without depletion of β-cells, which are used to model T2D from 1 to 3 phases." (PMID 34673835, 2021). "Mice homozygous for the mutation in Leptin receptor, do not sense satiety and develop sever hyperphagia leading to morbid obesity, chronic hyperglycemia, pancreatic beta cell atrophy and become hypoinsulinemic." (PMID 30814586, 2019). "For example, it has been shown that re-expression of leptin receptors in the POMC neurons of leptin receptor deficient mice prevents hyperglycaemia, independent of leptin’s anti-obesity effect." (PMID 31506541, 2019). "Also, adenovirally-mediated re-expression of leptin receptors (LEPRs) only in the hypothalamic arcuate nucleus (ARC) was shown to be sufficient to ameliorate hyperglycemia in otherwise LEPR null mice." (PMID 24589844, 2014). "Leptin receptor-deficient db/db mice develop hyperglycemia by 2 months of age, but not all db/db mice develop it." (PMID 24809394, 2014). "In addition, hyperglycosylated isoforms of the long form of leptin receptor (150 kDa) were particularly favored by hyperglycemia." (PMID 24260287, 2013). "Moreover, active JAK2 and leptin receptor were almost completely colocalized under hyperglycemia providing strong evidence that leptin receptor signaling is directly induced by high glucose levels in mammary epithelial cells." (PMID 24260287, 2013). "Interestingly, in a study of diabetic mice (leptin receptor mutation) crossed with CaMKII knockout mice, there was no development of hyperglycemia, but normal glucose uptake into muscle, reduced hepatic glucose synthesis, and the absence of retinopathy." (PMID 38064002, 2024). "Likewise, the short isoform of leptin receptor was increased under hyperglycemia." (PMID 24260287, 2013). "Thus, our observation that hyperglycemia upregulates hyperglycosylated forms of leptin receptor indicates that high glucose not only affects receptor levels, but may also affect the binding affinity of the receptor for its ligand." (PMID 24260287, 2013). "To determine whether elevated serine disposal is specific to leptin receptor-deficient db/db mice or is more generally attributable to impaired insulin signalling, we treated C57BL/6J mice with vehicle or streptozotocin (STZ) to induce insulin deficiency, hyperglycaemia and fat loss." (PMID 36697822, 2023). "Leptin receptor-mutant (db/db) mice were reported as a popular animal model of T2DM, with syndromes including hyperglycemia, obese and hyperlipidemia, etc.." (PMID 28883792, 2017).
Hyperglycemia (continued). "Prenatal hyperglycemia induces strong changes in later hypothalamic expression of INSR, LEPR, GLUT1, and GLUT3 mRNA." (PMID 25811618, 2015). "Since there is significant cross-talk between leptin receptor, insulin, and IGF1R/IGF1 (insulin-like growth factor) signaling pathways, we assessed the effect of hyperglycemia on key intermediates within each of these pathways." (PMID 24260287, 2013). "In the current study, increased levels of both long and short forms of leptin receptor, as well as, increased levels of GRB2, phospho-STAT3, and phospho-JAK2 were observed under hyperglycemia." (PMID 24260287, 2013). "Several carbohydrate metabolism genes involved in metabolism of monosaccharide and carbohydrate and hyperglycemia (e.g. CPT1A, GALK1, INS, LEPR, PRLR and SCD) are highly expressed in mouse CPE and only lowly in human CPE." (PMID 24391755, 2013). "A lack of either Lep or the leptin receptor (Lepr) in mice and humans results in obesity, hyperglycemia, and IR." (PMID 37071471, 2023). "Studies using mouse models have shown that restoration of leptin receptor expression in hypothalamic arcuate nucleus (ARH) neurons normalizes hyperglycemia in obese and diabetic mice." (PMID 32131811, 2020). "Leptin receptor signaling classically utilizes the JAK2/STAT3 signaling pathway; therefore, we assessed the levels of JAK2 and STAT3 activation under high glucose conditions and found that hyperglycemia resulted in increased JAK2 phosphorylation in all cell lines within 72 hr." (PMID 24260287, 2013).
breast cancer (116 papers, 2006 to 2026). A primary or metastatic malignant neoplasm involving the breast. "Poor prognosis in breast cancer has been associated with elevated expression of the leptin receptor (LepR) and FGFR1 amplification, and co-expression of the FGFR1 gene and leptin protein copy number has been observed in primary breast tumours." (PMID 39251829, 2024). "By menopausal status, LEPR gene rs1137100-AA genotype carriers conferred a significantly reduced risk of breast cancer compared with GG genotype carriers (OR: 0.23, 95% CI: 0.07 to 0.82) in both premenopausal and postmenopausal women." (PMID 37274250, 2023). "Overall, LEP gene rs7799039-G allele and LEPR gene rs1137100-A allele were associated with reduced breast cancer risk relative to the corresponding reference alleles, and the risk was close to statistical significance." (PMID 37274250, 2023). "Five SNPs of LEP and two of LEPR were chosen to evaluate the correlation of selected SNPs with breast cancer susceptibility among women in northern and eastern China." (PMID 35223490, 2022). "Leptin appears to be a key driver in energy homeostasis and breast cancer tumorigenesis, and its expression is associated with AT mass, BMI, and leptin receptor (OB-R)." (PMID 35701840, 2022). "Based on these results, in the current study, we selected 7 polymorphisms located in the LEP and LEPR genes and identified the association with breast cancer risk in northern and eastern Chinese Han females by conducting a multicenter case–control study." (PMID 35223490, 2022). "Studies have identified genetic variants of LEP and LEPR correlated with susceptibility of various malignant tumors, including breast cancer." (PMID 35223490, 2022). "Our current study found a significant association between the LEPR rs1137101 and rs4655555 variants and decreased risk of breast cancer in a Chinese Han population." (PMID 35223490, 2022). "In conclusion, our study provides evidence that rs1137101 and rs4655555 of the LEPR gene are associated with breast cancer susceptibility in Chinese women." (PMID 35223490, 2022). "In subgroup analyses, the GA and GA + AA genotypes of LEPR rs1137101 associated with decreased breast cancer risk in the subgroup of BMI ≤ 24 kg/m2 or WHR ≥ 0.85 after Bonferroni correction." (PMID 35223490, 2022). "Our current study aimed at determining the influence of single-nucleotide polymorphisms (SNPs) in the genes coding for LEP and LEPR on breast cancer risk." (PMID 35223490, 2022). "To further identify the downstream associated genes of breast cancer risk-related variants, we found that 2 cis-eQTL genes (LEPR and LEPROT) were associated with rs4655555 based on the eQTLGen database." (PMID 35223490, 2022). "We further identified that the genotype of LEPR rs1137101 was associated with decreased breast cancer risk under the dominant genetic model in the subgroup of WHR ≥ 0.85 regardless of BMI by stratified analysis." (PMID 35223490, 2022). "LEPR rs1137101 decreased ER+/PR+ breast cancer risk in the dominant genetic model (GA + AA vs. GG, adjusted OR = 0.727, 95% CI = 0.568–0.930, p = 0.011) and the co-dominant genetic model (GA vs. GG, adjusted OR = 0.739, 95% CI = 0.575–0.951, p = 0.019)." (PMID 35223490, 2022). "To evaluate the potential causal function of rs4655555-associated genes in breast cancer risk, based on the TCGA database, we found a higher expression of LEPR and LEPROT in breast cancer tumor tissues compared to that of adjacent normal tissues." (PMID 35223490, 2022). "A high expression of LEPR is significantly associated with poor OS of breast cancer patients, with HRs (95% CIs) of 1.68 (95% CI: 1.01–2.80)." (PMID 35223490, 2022). "The influence of LEP and LEPR genes polymorphisms on the body mass of women with breast cancer and control subjects was assessed." (PMID 33864589, 2021).
breast cancer (continued). "In these studies, we analyzed the contribution of LEP (2548G>A) and LEPR (109 Lys>Arg and 223Gln>Arg) genes polymorphisms to the risk of breast cancer development." (PMID 33864589, 2021). "The loss of LEPR expression in breast cancer was also observed to modulate the tumor microenvironment." (PMID 33799880, 2021). "Individual genotypes of LEPR polymorphism 109 Lys>Arg occur in the group of women with breast cancer with frequency 47% for WW, 44% for WV, 9%for VV, and the group of control subjects 50.5%, 37%, and 12.5%." (PMID 33864589, 2021). "In this meta-analysis, the associations of polymorphisms within paraoxonase 1 (PON1), leptin (LEP) and leptin receptor (LEPR) genes with susceptibility to breast cancer were comprehensively evaluated." (PMID 34452542, 2021). "In summary, we decided to evaluate the impact of LEP and LEPR genes polymorphisms on the development of breast cancer in women from the Greater Poland region." (PMID 33864589, 2021). "Paraoxonase 1 (PON1), leptin (LEP) and leptin receptor (LEPR) genes are good example of a GWAS-identified locus that has been implicated in development of breast cancer." (PMID 34452542, 2021). "In summary, this meta-analysis aimed to summarize association between the PON1 rs662, rs854560 LEP rs7799039 and LEPR rs1137101 polymorphisms and susceptibility to breast cancer." (PMID 34452542, 2021). "Higher leptin receptor expression levels were associated with an increased incidence of bone metastasis in breast cancer patients." (PMID 33799880, 2021). "High LEPR expression is associated with poor outcomes in patients with thyroid cancer, breast cancer, cervical cancer, ovarian cancer, and gastric cancer." (PMID 33799880, 2021). "Leptin-deficient obese mice had decreased mammary tumor growth relative to wild type in syngeneic models, and leptin receptor (ObR)-deficient mice (with high leptin levels), showed greater mammary tumor growth with syngeneic cancer models." (PMID 33604295, 2020). "In this study, we leverage public gene expression datasets to evaluate the associations between FGFR1, leptin, and the leptin receptor (LepR) in breast cancer." (PMID 33019728, 2020). "Independently, high FGFR1 protein expression or high LepR protein expression is implicated in the poor prognosis of breast cancer patients." (PMID 33019728, 2020). "Collectively, these data demonstrate a positive association between FGFR1, leptin, and the LepR in human primary breast cancer and a much weaker association in metastatic tumors." (PMID 33019728, 2020). "The results indicated that higher leptin receptor levels in breast cancer cells are associated with increased incidence of bone metastasis in breast cancer patients." (PMID 32836215, 2020). "The correlation between KHDRBS1 expression and the expression of LEPR strengthens the idea that KHDRBS1 is implicated downstream of the LEPR in metastatic cells, as has been reported in breast cancer cells." (PMID 33213024, 2020). "Further correlation analysis suggested that PAI-1 was positively associated with LEPR in different breast cancer cell lines." (PMID 33371368, 2020). "These mice, with an intact central leptin signaling and a deficient peripheral leptin receptor, exhibited a decreased mammary tumor growth and progression." (PMID 30634494, 2019). "Breast cancer cells overexpress leptin receptor, hence becoming highly susceptible to the influence of elevated leptin levels typically seen in obese patients." (PMID 30823902, 2019). "In the polymorphism of LEP G2548A, the associated allele A is the risk factor for the development of breast cancer, while, in the LEPR Q223R polymorphism, the R allele is linked to the development of the disease." (PMID 30404206, 2018). "In animal experiments, deficiency of the leptin receptor resulted in failure of mammary tumor formation." (PMID 28160559, 2017).